HIF1A (hypoxia inducible factor 1 subunit alpha)
Diseases named in the same sentence as HIF1A in open-access papers (continued):
Sharing a sentence is not in itself a finding about the gene and the disease.
Sepsis (continued). "Our findings suggest that EDA, by inducing the HIF-1α/HO-1 pathway in advance of sepsis, can reduce cardiac oxidative stress and prevent septic cardiac dysfunction, which eventually improves animal survival." (PMID 29765498, 2018). "Here, for the first time, we demonstrated that EDA pretreatment induces HIF-1α in the myocardium and prevents myocardial dysfunction during sepsis." (PMID 29765498, 2018). "More importantly, HIF-1α is a transcription factor that induces IRAK-M expression in monocytes in the mice model of sepsis." (PMID 30622459, 2018). "In summary our results propose that the temporal dynamics of the myeloid HIF-1α response during LPS induced sepsis has significant consequences on both metabolic and inflammatory signaling pathways and clinical symptomatology." (PMID 30524296, 2018). "We also found that CLP rats treated with rapamycin had lower expression of HIF-1a in their myocardium, indicating that rapamycin improved myocardial anoxia in the sepsis model." (PMID 30050390, 2018). "Our results show that myeloid HIF-1α activation is an acute control element of the glycemic state during sepsis." (PMID 30524296, 2018). "Thereby, the current study aims to investigate the effect of miR-31 on intestinal barrier dysfunction through the NF-κB/HIF-1α pathway by targeting HMOX1 in sepsis." (PMID 30340459, 2018). "HIF-1α expression was statistically significantly higher in the shock patients compared to the controls and the reasons of shock were sepsis (78%), hemorrhage (18%), and cardiac dysfunction (4%)." (PMID 29026849, 2017). "It has been shown that KLF2 and hypoxia induced factor-1 alpha (HIF-1α) signaling plays a role in inflammatory regulation induced by Gram-positive endotoxin-mediated sepsis." (PMID 29125549, 2017). "Thus, in addition to the known effects on inhibition of proinflammatory gene expression in myeloid cells, KLF2 in association with HIF-1α could efficiently inhibit the Gram-positive endotoxin-induced effects in sepsis and can efficiently reduce clinical symptoms." (PMID 29125549, 2017). "Decreased HIF-1α mRNA expression inversely correlates with sepsis severity, i.e., with greater HIF-1α mRNA expression and intracellular HIF-1α protein suppression in patients with higher Simplified Acute Physiology Score II (SAPS II)." (PMID 27515179, 2016). "HIF-1α SNP frequencies in our Caucasian cohort with sepsis revealed only a single homozygous TT-genotype carrier (0.8 %), whereas 17.6 and 81.6 % carried the heterozygous CT- and homozygous CC-genotypes, respectively." (PMID 27515179, 2016). "With persistent inflammation, HIF-1α is suppressed in vitro and even in patients with sepsis, possibly to counter regulating an overwhelming inflammatory response." (PMID 27515179, 2016). "Genetic manipulation of HIF-1α in classical animal models of inflammation and neurodegeneration, including sepsis, rheumatoid arthritis and chronic cutaneous inflammation and stroke have shown that HIF-1α exerts a profound influence on disease progression." (PMID 26213713, 2015). "Upstream of FoxM1, the transcription factor HIF-1α (hypoxia-inducible factor 1-alpha) plays a pivotal role in ECs-mediated vascular repair and inflammation resolution, making it another attractive therapeutic target for sepsis-induced ARDS." (PMID 40476000, 2025). "For instance, in sepsis models, exosomes (communication module) inhibit HIF-1α-mediated glycolysis (metabolic reprogramming), subsequently suppressing the NLRP3 inflammasome (inhibition module) and promoting macrophage polarization toward the M2 phenotype (reprogramming module)." (PMID 41488628, 2025). "Modulating the activity of HIF-1α presents a promising therapeutic strategy for sepsis." (PMID 41041277, 2025). "Furthermore, a separate study demonstrated that rosmarinic acid (RA) inhibits lipopolysaccharide (LPS)-induced or sepsis-induced microglial M1 polarization in sepsis-surviving mice via the RACK1/HIF-1α pathway." (PMID 41296787, 2025).
Sepsis (continued). "Elucidating the seemingly paradoxical role of HIF-1α in sepsis is the core of future research." (PMID 41244772, 2025). "Thus, sepsis-induced hypoxia activates HIF-1α, which drives VEGF-mediated angiogenesis and promotes the expression of genes involved in invasion and metastasis." (PMID 40563999, 2025). "Alveolar macrophages (AMs) mainly rely on mitochondrial oxidative phosphorylation (OXPHOS) in the resting state, but during sepsis, they switch to glycolysis through HIF-1α-mediated metabolic reprogramming, resulting in excessive secretion of pro-inflammatory cytokines." (PMID 41244772, 2025). "Under hypoxic conditions HIF-1α stability increases promoting glycolysis and IL-1β release however in sepsis FGF21 suppresses M1 activation by promoting autophagic degradation of HIF-1α, while in atherosclerosis, pyruvate carboxylase exacerbate inflammation via HIF-1α." (PMID 41459510, 2025). "Furthermore, HIF-1α, a key regulator in sepsis and ARDS, has been recognized as a potential target for developing therapies to treat these conditions." (PMID 40887582, 2025). "However, it has been found that in sepsis-associated ARDS, upregulation or down-regulation of HIF-1α leads to the same endpoints seemingly contradictory, such as reducing oxidative stress, but the mechanism behind it involves a complex mechanism of action." (PMID 40887582, 2025). "However, other studies have revealed that both HIF-1α mRNA and protein levels are decreased in leukocytes of septic patients, with this decrease inversely correlating with sepsis severity." (PMID 41562069, 2025). "Furthermore, a separate class of drugs enhances therapeutic outcomes in ARDS and sepsis by stabilizing HIF-1α, thereby augmenting its protective functions." (PMID 40887582, 2025). "Combining the regulation of HIF-1α with other metabolic treatments, like improving mitochondrial function, could provide a more effective treatment approach for sepsis." (PMID 41041277, 2025). "Previous studies have shown that inhibiting the expression of lactate dehydrogenase A (LDHA) by regulating the PI3K/Akt-HIF-1α pathway could suppress glycolysis and contribute to immune suppression of neutrophils during sepsis." (PMID 40420943, 2025). "Interestingly, rabeprazole, an effective inducer of HIF-1α, can promote vascular repair and resolution of sepsis-induced inflammatory lung injury through endothelial HIF-1α/FoxM1 signaling." (PMID 39712019, 2024). "This suppression may contribute to the reduced proliferation of lymphocytes observed with increased HIF-1α levels in early sepsis." (PMID 38539163, 2024). "Furthermore, AMPK activators such as metformin and limonin have been demonstrated to inhibit HIF-1α expression in mice, thereby reducing aerobic glycolysis and moderating sepsis-related inflammatory responses." (PMID 39712019, 2024). "Targeted knockout of PFKFB3 leads to a significant reduction in EC glycolysis and effectively inhibits the NF-κB and HIF-1α signalling-mediated endothelial inflammatory response, thereby impeding the onset and progression of pulmonary hypertension, sepsis, and acute lung injury in murine models." (PMID 38755659, 2024). "Interestingly, a report has indicated that human blood sepsis monocytes under ET expressed high levels of PD-L1 on their cell surface via the induction of HIF1α, and governed the impaired induction of T-cell proliferation during ET." (PMID 38742111, 2024). "Suppressing SOCS1 may promotes glycolysis and pro-inflammatory responses in sepsis murine bone marrow cells via the STAT3/HIF-1α axis This implies that EV-miRNA may promote the glycolysis of septic macrophages." (PMID 39744123, 2024). "Moreover, previous data on ADM expression in patients with sepsis had revealed a correlation between reduced HIF1A levels and lower ADM expression in peripheral leukocytes." (PMID 38714572, 2024).
Sepsis (continued). "Furthermore, during sepsis, hypoxia-inducible factor 1-alpha (HIF-1α) triggers the upregulation of glucose transporter 1 (GLUT1), enhancing glucose uptake into cells." (PMID 39544938, 2024). "The HIF-1α pathway and glycolysis are integral to the immune response to sepsis." (PMID 37434129, 2023). "First, HIF-1α activation was analyzed in monocytes from patients with sepsis and HVs." (PMID 37047205, 2023). "Since HIFs interfere with the expression of multiple important metabolic enzymes, and since HIFs use transcriptional co-factors, such as p300, which are also essential for the function of GR and PPARα, we aimed to investigate the role of HIF1α and HIF2α in more detail during sepsis, in the liver." (PMID 37006237, 2023). "Common differential expression of IMRGs was identified in blood monocytes and myocardium between sepsis and control groups, among which HIF1A and SLC25A37 might predict prognosis in septic cardiomyopathy." (PMID 36937929, 2023). "Because crosstalk of transcription factors in physiology and pathology is a commonly observed phenomenon, we hypothesized that HIF1α and/or HIF2α might play a role in the PPARα and GR dysfunction during sepsis." (PMID 37006237, 2023). "It is speculated that IFNγ also reverses sepsis-induced immunosuppression through the PI3K/AKT/mTOR/HIF-1α pathway." (PMID 37434129, 2023). "The authors identified regulatory genetic variants in this group that account for the upregulated expression of the genes HIF1A and EPAS1 (endothelial PAS domain protein 1), indicating that HIF genetic variants may be deterministic of host sepsis response." (PMID 37627293, 2023). "Interestingly, one of few studies on monocytes subjected to combined hypoxic/inflammatory stimulation demonstrated that hypoxia limits inflammation in sepsis through HIF-1a signaling, and instead promotes phagocytosis and tissue remodeling." (PMID 37753073, 2023). "Also dimethyloxalylglycine (DMOG), a PHD inhibitor leading to HIF1α stabilization, increased the survival of mice against LPS-induced endotoxemia, however it exacerbated disease severity in polymicrobial sepsis." (PMID 37006237, 2023). "Since hypoxia is associated with increased lipolysis, increased FFA levels in the blood, and impaired FFA β-oxidation, and p300 functions as a co-activator for PPARα, hepatic HIF1α and/or HIF2α might be involved in the declined PPARα signaling during sepsis." (PMID 37006237, 2023). "Furthermore, we have investigated the functional role of HIF1α and/or HIF2α during sepsis in more detail via hepatocyte-specific HIF1α and/or HIF2α knock-out mice with a focus on their role in the annihilation of the transcriptional function of GR and PPARα." (PMID 37006237, 2023). "Our present study indicated for the first time that HIF-1α may regulate neutrophil functions in sepsis via LDHA." (PMID 35090526, 2022). "The final aim was to determine whether Rabeprazole improves vascular repair and the resolution of sepsis-induced inflammatory lung injury via HIF-1α and FoxM1." (PMID 35563731, 2022). "The study suggests that up-regulation of HIF-1α may be a promising treatment for controlling sepsis." (PMID 35576220, 2022). "Enlightened by those studies, we would wonder that whether miR-124-3p could interact with SP1, thereby affecting HDAC4/HIF-1α axis to attenuate myocardial injury in sepsis." (PMID 35091534, 2022). "Further research using both human and mouse in vivo models on the actions and relations of IRAK3 to other molecules (glucocorticoids, TREM-1, HMBG1, and HIF-1α) and inflammatory regulators will clarify insights and may improve treatment of sepsis." (PMID 35167625, 2022). "Selective activation of HIF-1α may be an alternative effective and relatively safe approach for treatment of severe sepsis and ARDS." (PMID 35563731, 2022).
Sepsis (continued). "Furthermore, the expression level of HIF-1α was lower in the sepsis + BAY 87–2243 group (P < 0.05), and the protein expression levels of ZO-1, occludin and claudin-1 protein were significantly decreased (P < 0.05)." (PMID 35576220, 2022). "Furthermore, mice exposed to lower oxygen concentration had increased HIF1A stabilization and subsequently improved outcomes during polymicrobial sepsis." (PMID 36326834, 2022). "All in all, it was certified that miR-124-3p interacted with SP1 to suppress HDAC4, thereby ameliorating sepsis-induced myocardial injury, which may related to the knockdown of HIF-1α." (PMID 35091534, 2022). "Mice with EC-specific KO of Hif1a (Hif1a/Tie2Cre) exhibit impaired lung endothelial regeneration and vascular repair in contrast to wild type mice, despite similar levels of peak injury following sepsis challenge." (PMID 35563731, 2022). "Our study provides further evidence that vascular repair and the resolution of inflammatory lung injury is driven by HIF-1α and FoxM1 in ECs and that pharmacological activation of the HIF-1α/FoxM1 signaling axis is a putative therapeutic strategy for severe sepsis and ARDS." (PMID 35563731, 2022). "The transcription factor, HIF-1α is induced in monocytes from patients with sepsis, and upregulated IRAK3 mRNA and protein expression between 0.5h to 24h as well as reducing TNF-α and IL-6 expression at IT and LT in in vitro monocytes challenged with endotoxin." (PMID 35167625, 2022). "HIF-1α might signify an important and novel therapeutic target to improve neutrophil function during sepsis." (PMID 35090526, 2022). "miR-124-3p was lowly expressed while SP1, HDAC4, and HIF-1α were highly expressed in sepsis." (PMID 35091534, 2022). "However, further studies are needed to clarify the time-dependent and different effects of HIF-1α signal on intestinal mucosa during sepsis." (PMID 35576220, 2022). "HIF-1α is rapidly increased in murine LECs after endotoxemia sepsis challenge." (PMID 35053299, 2022). "Whether the body can increase metabolism, reduce the inflammation and oxidative stress response to address damage to the intestinal mucosal barrier in sepsis by upregulating HIF-1α expression is unclear." (PMID 35576220, 2022). "The mechanism through which HIF-1α and mitochondria affect sepsis-related diaphragm injury is unknown." (PMID 35163007, 2022). "HIF-1α is rapidly induced and stabilized in mouse lung vascular ECs after sepsis challenge." (PMID 35563731, 2022). "Further studies are at wanting to deeply decode the miR-124-3p/SP1/HDAC4/HIF-1α axis in sepsis." (PMID 35091534, 2022). "Thus, the identification of an existing HIF-1α inducer/activator has great clinical potential for the treatment of severe sepsis and ARDS." (PMID 35563731, 2022). "Our findings showed that HIF-1α protects the intestinal barrier function of septic rats by inhibiting intestinal inflammation and oxidative damage, our results provide a novel insight for developing sepsis treatment." (PMID 35576220, 2022). "Here, we sought to determine the role of myeloid HIF1α in the host response during pneumonia and sepsis caused by K. pneumoniae, a common gram-negative human pathogen." (PMID 34393650, 2021). "Together, these results suggest that HIF1α in alveolar macrophages, but not in neutrophils, is important for host defense against pneumonia-derived sepsis caused by K. pneumoniae." (PMID 34393650, 2021). "Moreover, HIF-1α deletion in murine macrophages was shown to offer protective effects against LPS-induced mortality, and the blockade of HIF-1α activity has been proposed to be a therapeutic target for treating LPS-induced sepsis." (PMID 33567713, 2021). "Taken together, we show that in the absence of HIF-1α, NK cells drive an accelerated skin regeneration programme at the expense of increased susceptibility to bacterial infections and sepsis." (PMID 34349124, 2021). "Modulation of mTOR/HIF-1α pathways regulates microglia’s immune response in sepsis." (PMID 34062710, 2021).
Sepsis (continued). "Thus, the metabolic changes in the immune system during sepsis as well as the inflammatory response in septic shock are tightly regulated by HIF-1α." (PMID 34447792, 2021). "The expression of HIF1α has been previously found to be a sepsis marker." (PMID 33345622, 2021). "Higher HIF1α expression levels were detected in whole blood cells from patients with septic shock, in line with the increased expression in the kidney as demonstrated here in sepsis-AKI." (PMID 33494815, 2021). "HIF-1α is a transcription factor involved in the regulation of inflammatory cytokines in sepsis." (PMID 33567713, 2021). "In this study, Leu was found to suppress monocyte infiltration, calpain activity, and mRNA expressions of inflammatory cytokines and HIF-1α, suggesting that Leu administration may attenuate muscle wasting in sepsis by its anti-inflammatory actions." (PMID 34884807, 2021). "This may be explained by sepsis-related inflammatory hypoxia and mechanical stretch-induced normoxic stabilization of HIF-1α in alveolar epithelia, which are maintained by the inhibition of SDH." (PMID 33567713, 2021). "Hence, it is possible that the protein NF-κB also engages in the sepsis immune response in the HIF-1α signaling pathway, which also awaits further study." (PMID 32089644, 2020). "Conversely, in the clinical study, the expression of protein PD-L1 was upregulated in the late phase of sepsis, while, in the animals' study, the protein PD-L1 expression was higher in the sepsis rat model group compared with the Ade-control group and the Ade-HIF-1α group." (PMID 32089644, 2020). "HIF-1α level shows increase in A. baumannii induced mouse sepsis model." (PMID 32391015, 2020). "This may be caused by MV-induced normoxic stabilization of alveolar epithelial HIF-1α, which is accomplished by inhibiting succinate dehydrogenase and sepsis-related inflammatory hypoxia." (PMID 32353952, 2020). "Moreover, we also found that the HIF-1α was activated in hypoxic conditions during the primary phase in sepsis, which then coactivated the signal transducer and activator of transcription 3 (STAT3) to engage in the inflammatory process." (PMID 32089644, 2020). "Understanding the combinatorial effects of endotoxin and mechanical stretch on HIF-1α signaling may allow for the clarification of the molecular mechanisms in the pathogenesis of ALI related to sepsis and MV." (PMID 32353952, 2020). "Therefore, monocytes undergo immunosuppression in the late phase of sepsis through the HIF-1α signaling pathway, which induced the upregulation of protein PD-L1 expressed on the monocytes." (PMID 32089644, 2020). "Therefore, monocytes undergo immunosuppression in the sepsis late phase through the HIF-1α signaling pathway." (PMID 32089644, 2020). "Another study showed that miR-208a-5p is elevated in the myocardium during sepsis and its inhibition could reduce the myocardial damage induced by inflammation, probably by influencing the NF-kB/HIF-1α signaling pathway." (PMID 33396834, 2020). "Similarly, co-stimulation of mice with LPS and the statin, simvastatin, decreased HIF-1α levels and protected against liver dysfunction in the early stage of sepsis." (PMID 31555665, 2019). "Taken together, these studies may suggest that HIF-1α has important temporal roles during sepsis; regulating the inflammatory response during the acute phase and regulating protective responses during the later stages." (PMID 31555665, 2019). "In addition, succinate has been shown to be partially derived from glutamine via the GABA shunt and inhibition of this pathway lowers succinate levels and in turn decreases HIF-1α stabilization in murine macrophages and sepsis." (PMID 31555665, 2019). "Furthermore, it has been shown that NET formation is regulated by post-transcriptional control of HIF1α expression following sepsis challenge and that pharmacological or genetic knockdown of HIF1α inhibits NET deployment." (PMID 31423111, 2019).